IL2 (interleukin 2)
Diseases named in the same sentence as IL2 in open-access papers (continued):
Sharing a sentence is not in itself a finding about the gene and the disease.
atherosclerosis (continued). "Release of cytokines such as TNF-alpha and interleukin-2 during inflammation or stress leads to endothelial dysfunction disruption of atheromatous plaques and hypercoagulability, all leading to acceleration of atherosclerosis." (PMID 28270112, 2017). "IL-2/anti-IL-2 complex (IL-2C) has been reported to rapidly increase Tregs in different diseases, including stroke, myasthenia, or atherosclerosis, and provides protective effects by inhibiting inflammation and substantially attenuating the progression of these diseases." (PMID 28713327, 2017). "In the context of CVD, IL-2 may influence inflammatory pathways, leading to vascular dysfunction, including endothelial permeability and leukocyte adhesion, which are key features of vascular diseases like atherosclerosis." (PMID 39857734, 2025). "Furthermore, SARS-CoV-2 leads to cytokine outburst, including IL-6, IL-1b, IL-2, IL-10, and monocyte chemoattractant protein-1 (MCP-1), which are also associated with vascular dysfunction and vascular disease such as atherosclerosis, abdominal aortic aneurysm, varicose veins and hypertension." (PMID 36211676, 2022). "Hence, alteration of IL-2 levels benefits bacterial establishment and may also contribute to progression of the inflammatory state in atherosclerosis, considering that IL-2 play an important role in the clonal expansion of regulatory T-cells." (PMID 22984628, 2012). "Seven core targets-IFNG, CXCL8, TNF, TGFB1, IL2, IL4, and RELA-were identified via network pharmacology, involving key pathways such as lipid-atherosclerosis, AGE-RAGE, and IL-17 signaling." (PMID 40708520, 2026). "Our study focused on pro-inflammatory cytokines, particularly IL-6, IL-2, and TNF-α, due to their involvement in the inflammatory cascade of atherosclerosis." (PMID 40265387, 2025). "For atherosclerosis, local delivery of IL-2 to atherosclerotic lesions or treatment with anti-CD3 and IL-2/anti-IL-2 mAb complexes led to a reduction in atherosclerosis due to Treg expansion in ApoE-/- mice." (PMID 36761778, 2023). "Leptin’s proinflammatory effects also increase cytokines such as TNF-alpha, IL-1, IL-2, IL-2 and MCP-1, leading to accelerated atherosclerosis, insulin resistance and endothelial dysfunction." (PMID 37371050, 2023). "Successful suppression of atherosclerosis is also possible with treatment using anti-CD3 antibodies and the IL-2 complex." (PMID 34445084, 2021). "Th1 cells play an important role in the development of atherosclerosis by secretion of inflammatory cytokines such as IFN‐γ, IL‐2, TNFα/β and M1 macrophages stimulation." (PMID 33230950, 2020). "Conversely, atherosclerosis is prevented by inducing Tregs with anti CD3 and IL-2/anti-IL2 or both monoclonal antibodies." (PMID 31653058, 2019). "The higher levels of cytokines in CAE, particularly IL-6, IL-8, IFN-γ, IL-1β, and TNF-α are similar to those in atherosclerosis, where TH1 enhances macrophage activation through IFN-γ and IL-2." (PMID 29337902, 2018). "One approach to do this is bytargeting pathways like IL-2 and boosting non-specific T regulatory cells.However, tolerogenic vaccinations against atherosclerosis-related antigens can beused to increase the number of certain T regulatory cells." (PMID 40160593, 2025). "Furthermore, anti-inflammatory/inflammation-regulatory genes (like IL7R, ANXA1, and KLRB1) and pathways (like regulation of IL-2 production) were decreased in CD4+ T cells (T_1, T_2, and T_3) from atherosclerosis compared with those from NC." (PMID 37706320, 2023).
atherosclerosis (continued). "Several proposed mechanisms have been elucidated, for example, human immunodeficiency virus, herpesviruses, and Chlamydia pneumoniae may accelerate atherosclerosis through the induction of TNF-α and IL-2 in response to antigens." (PMID 37104297, 2023). "Although the precise roles of IL-2 in atherosclerosis are not well clarified, substantial research evidences have demonstrated the potent roles of IL-2 in stimulating lymphocytes to produce inflammatory cytokines, such as IL-6, TNF-α, and IFN-γ." (PMID 31379468, 2019). "Recent studies have shown that the IL-2 immune complex, which comprises IL-2 and anti-IL-2 mAb (JES6-1), selectively expands Treg cells up to sixfold and effectively inhibits the development and progression of atherosclerosis in ApoE−/− mice." (PMID 27144181, 2016). "IL-2 therapy has also been evaluated in a clinical study treating hepatitis C virus (HCV), in which a strong increase in CD25+ FoxP3+ CD8+ Tregs was observed, a finding that could warrant further studies also in the context of atherosclerosis." (PMID 33383733, 2020). "Most probably, the amount of IL-2/IL-2 mAb used in murine models is not physiologically relevant and further work is required to titrate the dose of cytokine required to protect against atherosclerosis without inducing undesirable side effects." (PMID 28589929, 2017). "Considering the low expression of IL2 and IL4 mRNA in atherosclerotic plaques, the role of these cytokines may not be significant in atherosclerosis." (PMID 22509262, 2012). "Previous investigations have indicated the importance of these two inflammatory cytokines, IL-2 and IFN-γ, in the etiopathogenesis of various conditions such as atherosclerosis and ischemic and non-ischemic dilated cardiomyopathy, which could stand as the underlying cause of CHF development 7–9." (PMID 30090212, 2018).
glioma (73 papers, 2000 to 2025). A benign or malignant brain and spinal cord tumor that arises from glial cells (astrocytes, oligodendrocytes, ependymal cells). "Research into the use of IL-2 in glioma patients began as early as 1986, and a phase I trial investigating a glioma cell vaccine transfected with a gene encoding IL-4 showed promising clinical responses in patients with HGGs." (PMID 40113789, 2025). "The high-risk group displayed elevated expression levels of CA9, IL-2, and IL-6 in the glioma tissues." (PMID 39574472, 2024). "On the contrary, HOXC10 was positively associated with IL6/JAK/STAT3 and IL2/STAT5 signaling in glioma, and previous studies also indicated that these two signaling pathways were activated." (PMID 38154103, 2023). "Moreover, increased IL‐2 levels were negatively associated with anxiety symptoms (p = .00) and positively correlated with cognitive impairment in glioma patients." (PMID 32790154, 2020). "In addition, we suggest here that NFATc3 is a key positive regulator of RCAN1-4, COX-2; TNF-α; CXCR-3, GM-CSF and IL-2, known to be implicated in glioma growth." (PMID 31249342, 2019). "Another research group utilized engineered bone-marrow-derived myeloid cells releasing interleukin-2 (GEMys-IL2) in mice with low-grade gliomas that readily crossed the BBB and entered the TME to stimulate the immune cell response." (PMID 38893192, 2024). "GEMys-IL2 prolonged survival in mice with low-grade gliomas, suggesting the anti-tumor activity of IL-2 in the innate response within the glioma TME." (PMID 38893192, 2024). "To validate the findings obtained from the bioinformatic analysis, we conducted IHC assays for CA9 (a biomarker of hypoxia and glycolysis), IL-2, and IL-6 proteins in glioma tissues obtained from our research cohort." (PMID 39574472, 2024). "In a clinical trial conducted in 2004, autologous NK cells co-cultured with an irradiated human feeder cell line (HFWT) using RHAM-alpha medium supplemented with 5% autologous plasma and IL-2 were injected in nine adult recurrent-glioma patients." (PMID 37444531, 2023). "In summary, while appropriate doses of IL-2 remain an important component of glioma immunotherapy, IL-2 needs to be used in combination with other immunotherapeutic strategies to maximize synergistic therapeutic effects." (PMID 38259287, 2023). "Six unresectable recurrent-glioma patients were recruited to evaluate the safety and feasibility of intracranial GRm13Z40-2 T cells combined with recombinant human IL2 (rhIL2, aldesleukin)." (PMID 37444531, 2023). "Its inhibition of rat glioma tumor-bearing is by enhancing the activity of NK cells and T cells, and increasing the concentration of serum interleukin-2 (IL-2) and TNF-α." (PMID 36686745, 2022). "IL-2 was first studied in glioma patients in 1986, which the combined IL-2 and tumor vaccination was observed with remarkable side effects." (PMID 35135556, 2022). "The result shows that CYB561D2 over-expressing glioma cells inhibited IL-2 secretion of mouse T cells in a STAT3-dependent manner." (PMID 34372858, 2021). "GLP has been shown to prevent glioma growth in glioma-bearing rats by increasing the concentration of serum interleukin-2, tumor necrosis factor-α, and interferon-γ, as well as enhance the cytotoxic activity of natural killer cells and T cells." (PMID 34069721, 2021). "In conclusion, behavioral symptoms are prevalent in glioma patients prior to surgery, and behavioral symptoms are associated with inflammatory factors such as IFN‐γ and IL‐2." (PMID 32790154, 2020). "Alternate methods have been reported, i.e., (i) OKT3 stimulation of peripheral T-cells along with IL-2 was used to treat nine patients with glioma." (PMID 29058035, 2018). "Glioma stem cells expressed lower levels of the PD-L1 than those of differentiated glioma cells, which contributed to the higher sensitivity of glioma stem cells to the cytotoxicity of the IL-2-activated NK cells." (PMID 29250533, 2017).
glioma (continued). "Mice implanted with gliomas expressing both IL-10 and IL-2 had significantly smaller (99% smaller) tumor sizes and increased T-cell infiltration at 14 days post-implantation compared to mice with IL-10−/IL-2− tumors." (PMID 26217588, 2015). "In a rat glioma model, recombinant vaccinia virus expressing the cytokines IL-2 or IL-12 resulted in tumor growth inhibition after intratumoral injection." (PMID 26056588, 2014). "LAK cells and IL-2 have been safely administered within the CNS resulting in improved long-term survival in patients with recurrent glioma." (PMID 24273748, 2013). "In previous work we have shown that γδ T cell cultures cultured ex vivo using a combination of anti-CD2, OKT-3, and IL-2 are cytotoxic to high-grade gliomas in vitro and to human xenograft tumors in immunodeficient mice." (PMID 23950874, 2013). "As with other cellular effectors, the immunosuppressive environment of malignant gliomas suppresses NK activity; T cells from patients with gliomas produce decreased amounts of IL-2 and IFN-γ." (PMID 24273748, 2013). "Lymphokine-activated killer (LAK) cells generated from PBMC by co-culture with IL-2 have been reported to selectively kill glioma cells in vitro and when placed into the resection cavity with minimal systemic or neurological side effects." (PMID 23433400, 2013). "As with NSCs, initial studies of MSCs against experimental gliomas involved the overexpression of a therapeutic cytokine (IL-2), resulting in augmented antitumor effect (compared to MSCs alone) and prolongation of animal survival." (PMID 24202446, 2013). "When IL-2 or interferon-γ (IFN-γ) transduced fibroblasts were coinjected with the murine GL261 glioma, the glioma cells were rejected by the recruited NK and LAK cells." (PMID 21437175, 2010). "Micewith an intracerebral (i.c.)glioma treated solely by intratumor injectionswith allogeneic cells genetically modified to secrete IL-2 survivedsignificantly longer than mice in various control groups." (PMID 18509487, 2008). "In gliomas, Tregs can inhibit dendritic cells, antigen presenting cells and other lymphocytes inhibiting the secretion of IL-2 and IFN-γ and promoting the secretion of TGF-β and indoleamine-2,3-dioxygenase (IDO), thus maintaining the immunosuppressive microenvironment." (PMID 40071070, 2025). ",12 (R)-2HG in the TME may impair production of IFNγ and IL-2 by CD4+ and CD8+ T cells as well as impacting myeloid cell populations, for example immunosuppressive glioma-associated macrophages generated due to altered tryptophan metabolism." (PMID 41138165, 2025). "In this context, pro-immunogenic mediators interferon-gamma (IFN-γ), tumor necrosis factor-alpha (TNF-α), and interleukin-2 (IL-2) have been shown to be upregulated in glioma surroundings after injection of miR-124 mimics, leading to a significant anti-glioma therapeutic impact." (PMID 39007129, 2024). "To evaluate the combined impact of the developing glioma and SorLA loss from host cells on the tumor microenvironment, we first assayed the levels of selected cytokines (TNFα, MIP2, CCL5, CXCL1, IL1β, IL2, IL6, and IL10) in the tissue lysates derived from tumor-bearing and tumor-free hemispheres." (PMID 38499808, 2024). "Interleukin-2 (IL-2) has been extensively studied for the immunotherapy of gliomas." (PMID 38259287, 2023). "In an autologous cytotoxicity assay, where peripheral blood mononuclear cells isolated from glioma patients were activated by IL-2 and co-incubated with the glioma cells from the same patient, treatment with AP 12009 restored their cytotoxic activity against glioma cells." (PMID 36010607, 2022). "For the upregulated genes in the Ad-SGE-REIC-treated U87ΔEGFR glioma brain tissue compared with the control, 14 significantly enriched pathways were identified, including the Notch Signaling Pathway, IL-2 Signaling Pathway, and TNF-alpha NF-kB Signaling Pathway." (PMID 36006934, 2022).
glioma (continued). "Moreover, combination therapy of glioma with recombinant vaccinia virus mediated IL2 expression, resulted in significant tumor inhibition with concomitant elevation of NK, Mac-1+ and NKT cells in blood and IFNγ and TNFα expression in tumors." (PMID 33790740, 2021). "However, IL‐2 is not only a pro‐inflammatory cytokine, but also an important cytokine of antitumor immunity in glioma (Rosenberg, Lotze, & Mulé, 1988)." (PMID 32790154, 2020). "Notably, cell targets with low surface EGFR expression relative to A431 were also efficiently lysed, although production of IL-2, TNFa and IFNg was lower when glioma cell lines were used as targets compared to A431." (PMID 31903167, 2019). "For instance, PBMCs were harvested for cellular therapy and CTL were generated directed against autologous (glioma) tumor cells (using a mix of PBMCs, autologous tumor cells and recombinant IL-2), followed by in situ administration (108 up to 109 T-cells i.t.)." (PMID 29058035, 2018). "In turn, IL2, the second key gene of RA, is crucial to regulation of the immune response, which can stimulate B-cells, monocytes, lymphokine-activated killer cells, natural killer cells, and glioma cells." (PMID 29851858, 2018). "IL2 has been used for therapy in glioma which increased the patient’s survival." (PMID 26390214, 2015). "In addition to MSC-delivered IL-2, more recent animal studies have used transduced MSCs to deliver IL-7, IL-12, or IL-18 in glioma xenografts." (PMID 24202446, 2013). "The present study was designed to determine whether IL-2 and histamine, alone or in combination, can induce anti-tumour effects in an orthotopic rat glioma model." (PMID 10952789, 2000). "Additionally, DEXs loaded with chaperone-rich cell lysates (CRCLs) derived from GL261 glioma cells promoted proliferation and activity of CD4+ and CD8+ T cells, enhanced T cell infiltration in intracranial glioma tissues, and induced the generation of anti-tumor cytokines, including IL-2 and IFN-γ." (PMID 34513718, 2021). "This is the first study to provide a detailed description of the tumor immune response in glioma patients after treatment with an OV, through the detection of Tregs and several activation markers for immune cells, including perforin, granzyme B, interferon-γ, interleukin 2 (IL-2), CD40L, and CD25." (PMID 30261620, 2018). "Thus, increased pSTAT-5 responsiveness to IL-2 may suggest that the DC vaccine has overcome the immunosuppressive effects of the tumor and effectively primed glioma-specific T cells." (PMID 24883189, 2014). "Furthermore, intracerebralinjection of fibroblasts genetically engineered to secrete IL-2 into anestablished intracerebral glioma was effective both in prolonging survival andstimulating a systemic antitumor immune response as measured in the spleencells using an IFN-γ ELISPOT assay." (PMID 18509487, 2008). "Autologous dermal primary fibroblasts transduced with a retrovirus to express IL-2 or IL-12 have already been used in clinical trials to treat two types of tumour, and IL-2 engineered syngeneic fibroblasts have also been injected intracerebrally to treat experimental glioma." (PMID 17595664, 2007). "We concluded then that nonantigen specific, exogenously administered CD8+ T cells can indeed accumulate within gliomas, despite tumor-imposed T cell sequestration, with IL-7 ALT accumulating intratumorally at a greater rate than IL-2–ALT." (PMID 40244705, 2025). "Using ELISAs and media from our primary mouse glioma cell lines cultured alone or cocultured with naïve CD8+ T cells, we assessed the production of proinflammatory cytokines IL-2, IFNγ, and TNFα." (PMID 39601621, 2024).